GOT1 (glutamic-oxaloacetic transaminase 1)
Diseases named in the same sentence as GOT1 in open-access papers (continued):
Sharing a sentence is not in itself a finding about the gene and the disease.
tumor (continued). "GOT1 (Glutamate oxaloacetate transaminase 1) plays a pivotal role in metabolizing glutamine to produce nicotinamide adenine dinucleotide phosphate (NADP+) and nicotinamide adenine dinucleotide (NAD+), thereby supporting redox balance and tumor growth." (PMID 40732339, 2025). "As FOXC2 was only downregulated in GOT1 cells treated with CdML2T, TE may be affecting the secreted proteins of LX2 cells, which subsequently impairs the expression of this gene in the tumour cells." (PMID 40998421, 2025). "In ANXA1-knockdown cells, the levels of aspartat and glutamate were significantly reduced compared to controls, overexpression of GOT1 in ANXA1 knockdown cells reversed the stabilizing effect of ANXA1 knockdown on GOT1, a trend also observed in the xenograft tumor model." (PMID 40390008, 2025). "In PDAC cells, tumor Asp availability was maintained by both de novo synthesis and alternative extracellular sources in the absence of GOT1/GOT2 in vivo." (PMID 39777342, 2024). "As upregulated glutamine catabolism is essential for tumor but dispensable for normal cells, inhibiting enzymes like GOT1 in the glutamine catabolic pathway leads to increased levels of reactive oxygen species (ROS), reducing the levels of GSH and ultimately inhibiting tumor growth." (PMID 38218942, 2024). "In our previous study on effects on tumor volume, injection of 30 MBq 177Lu-octreotate with and without A1M reduced GOT1 tumor volume to almost 30% after 7 days in a similar way9." (PMID 37076494, 2023). "Summarizing all these data, co-injection with A1M did not negatively influence the effects of 177Lu-octreotate on GOT1 tumor tissue at any of the studied time-points." (PMID 37076494, 2023). "To ensure a maintained therapeutic effect, we previously demonstrated that A1M does not affect the 177Lu-octreotate induced decrease in GOT1 tumor volume." (PMID 37076494, 2023). "All GOT1 tumor sections, irrespective of treatment, contained weak cytoplasmic staining of TNFRSF10B." (PMID 37076494, 2023). "We therefore conducted the present study to investigate the response in GOT1 tumor tissue when exposed to 177Lu-octreotate with or without A1M." (PMID 37076494, 2023). "P14 CD8+ tumor-infiltrating lymphocytes recovered from B16-GP33–41 tumors expressed significantly higher levels of Got1 than those recovered from B16-OVA tumors, indicating that TCR stimulation induced Got1 expression." (PMID 37813964, 2023). "Since our results showed an upregulation of TNFRSF10B after irradiation in GOT1 tumors at both time points, regardless of A1M administration, it seems likely that A1M can affect normal and tumor tissues differently." (PMID 37076494, 2023). "Recent studies have shown that SIRT5 depletion enhances glutamine and glutathione metabolism and promotes tumorigenesis through acetylation-mediated glutamate oxaloacetate transaminase 1 (GOT1) activation, while the SIRT5-selective activator MC3138 inhibits the proliferation of tumor cells." (PMID 37196115, 2023). "Altogether, this indicates that A1M does not reduce the early anti-tumor effect of 177Lu-octreotate on GOT1 tumors." (PMID 37076494, 2023). "In this study, we have found that HGD and GSTZ1 regulate the level of fumarate by metabolizing tyrosine, and by affecting GOT1 and GOT2 to coordinate amino acid metabolism and energy metabolism, determine the energy production pathway of tumor cells, and ultimately regulate the cell cycle." (PMID 35562974, 2022). "Glutamate oxaloacetate transaminase 1 (GOT1) and glutamate oxaloacetate transaminase 2 (GOT2) are both crucial for promoting tumor progression by regulating glutamate metabolism because transaminases generate α-ketoglutarate and indirectly participate in the TCA cycle." (PMID 35757505, 2022). "Moreover, knock-down of GOT1 in LNCaP and PC3 cells resulted in a significant decrease in cell viability, consistent with previous studies where GOT1 repression suppressed tumor growth in different tumors." (PMID 35158864, 2022).
tumor (continued). "Most protein levels of GDH1 were up-regulated in glucose-poor tumor tissues, simultaneously accompanied by decreased GOT1 protein levels, suggesting an underlying negative correlation between GDH1 and GOT1." (PMID 35154470, 2022). "The expression levels of BNIP3 and GOT1 decreased gradually with the increase in grades, but RRM2 increased gradually with the increase in clinical grades and stages, which revealed that three target genes were closely related to tumor progression." (PMID 35350243, 2022). "BNIP3 and GOT1 were downregulated gradually with the increase in the grade, but RRM2 increased gradually with the increase in the grade and stage, which revealed that three target genes were closely related with tumor progression." (PMID 35350243, 2022). "Moreover, six paired fresh tumor tissues and paraneoplastic tissues from children with MRTK were collected to validate the expressions of P4HA1, MLLT11, AURKA, and GOT1 in clinical samples via real-time fluorescence quantitative PCR and Western blot." (PMID 35558559, 2022). "We show that sensitivity to GOT1 knockdown varies among the cultures in this panel, is dispensable in non-transformed human lines, and that GOT1 inhibition stunted growth in tumor models." (PMID 34381026, 2021). "While no tumor regressions were observed, the combination of GOT1 and BSO significantly slowed tumor progression compared with single treatment arms." (PMID 34381026, 2021). "The canonical type refers to a phenotype in which tumors rely on glutamate dehydrogenase (GLUD1) for glutamine utilization; whereas non-canonical type refers to a phenotype in which tumor rely on aspartate transaminase (GOT1) for glutamine utilization." (PMID 25719198, 2015). "GOT1 knockdown significantly impaired tumor growth in PDA but not CRC." (PMID 31908776, 2020). "The expression of GOT1 could be regulated by oncogene KRAS or other regulators like non-coding RNAs, affecting Asp synthesis, NADPH production, glucose metabolism, as well as other metabolic pathways, and then tumor cells rewired metabolism to support their proliferation." (PMID 39777342, 2024). "Thus, GOT1 inhibits tumor growth by inhibiting proliferation, rather than inducing cell death." (PMID 34381026, 2021). "Collectively, these results indicated that while the pathway machinery in PDA and CRC are intact and functional, the differential dependence on GOT1 may result from distinct metabolic pathway activity, rather than enzyme expression, between these two tumor types." (PMID 31908776, 2020). "In this study, we provide evidence that STUB1 acts as a suppressor of tumor cell proliferation by controlling aspartate biosynthetic pathways through GOT2, not GOT1." (PMID 40651940, 2025). "Triple-negative breast cancer (TNBC) cell lines also overexpress GOT1, which controls intracellular ROS levels by producing NADPH, in turn promoting tumor growth." (PMID 36959802, 2023). "Knockdown of GDH, AIAT, or GABAT, but not GOT1, GOT2, or PCb, significantly reduced tumor growth." (PMID 40822358, 2025). "Tumor cells not only undergo glycolysis to produce NADPH to maintain cellular redox balance, but can also generate NADPH through a non-canonical glutamine pathway mediated by GOT1." (PMID 36497150, 2022).
cancer (64 papers, 2013 to 2026). A tumor composed of atypical neoplastic, often pleomorphic cells that invade other tissues. "GOT1 was crucial for the metabolic adaptation of cancer cells, particularly in those harboring KRAS mutations, where it coordinated glycolysis and oxidative phosphorylation pathways to support cell proliferation." (PMID 40390008, 2025). "The shRNA-mediated inhibition of GOT1 expression enhances cancer cell sensitivity to doxorubicin by causing doxorubicin-induced ROS generation." (PMID 36959802, 2023). "In KRAS-mutated cancer cells, inhibition of glutamate oxaloacetate transaminase 1 (GOT1) increases the sensitivity to glucose deprivation, GOT1 is critical to provide oxaloacetate at low glucose to maintain the redox homeostasis." (PMID 36778129, 2023). "In these cancer conditions, respiration deficiency can lead to metabolic rewiring in which GOT1 becomes the main aspartate producer (left)." (PMID 34827664, 2021). "KRAS mutated cancer cells were recently shown to rely on GOT1 to support long-term cell proliferation." (PMID 29751795, 2018). "Evidence shows that cancer cells with a KRAS mutation or an electron transport chain defect depended on glutamate oxaloacetate transaminase 1 (GOT1) to support cell proliferation." (PMID 29751795, 2018). "Moreover, GOT1 is overexpressed in many cancers, and its association with the occurrence and progression of numerous tumors has been reported." (PMID 40390008, 2025). "In most cases, elevated expression of GOT1 in cancer is associated with poor prognosis." (PMID 39777342, 2024). "Furthermore, both studies confirmed an association of GOT1 with cancer progression and acquisition of castration resistance, and that its knockdown suppresses cancer progression." (PMID 37714917, 2023). "Moreover, higher levels of GOT1 were linked to poor survival in certain types of cancers." (PMID 29751795, 2018). "Thus, from a basic science perspective further exploration is warranted and similarly, it remains to be determined whether the GOT1-status associated prognostic differences are present in other glutamine-addicted cancers as well." (PMID 25595905, 2015). "The results showed that glycolysis‐related genes, such as Nasp, Got1 and Taldo1, were highly expressed in the cancer cells of KAR mice." (PMID 40621620, 2025). "Compared to the NC group, the Sh1-GOT1 group exhibited a marked reduction in the percentage of EdU-positive cells, indicating that GOT1 knockdown slowed cancer cell proliferation." (PMID 41327788, 2025). "The expression of GOT1 in the four cancer cell lines was tested by WB, and TU686 and D562 were selected for subsequent experiments because of their high expression of GOT1." (PMID 41327788, 2025). "Previous studies have indicated that GOT1 has emerged as a pivotal factor in the investigation of cancer metabolism." (PMID 41246353, 2025). "In summary, our study demonstrated that down-regulating the expression of GOT1 can inhibit proliferation, accelerate apoptosis of cancer cell lines, and increase cisplatin sensitivity." (PMID 41327788, 2025). "We found that the mRNA and protein levels of ALDH3A1 decreased after GOT1 knockdown in cancer cells, which was consistent with the sequencing results." (PMID 41327788, 2025). "The immunohistochemical results of the tissue microarray demonstrated high expression of GOT1 in cancer tissues." (PMID 41327788, 2025). "The effects of GOT1 knockdown on cancer cell proliferation were confirmed using CCK8, wound healing assays, colony formation assays, and EdU assays." (PMID 41327788, 2025). "GOT1 expression is upregulated in cancers such as pancreatic ductal adenocarcinoma, colorectal cancer, breast cancer, prostate cancer, acute myeloid leukemia, and hepatocellular carcinoma." (PMID 40390008, 2025). "Inhibition of GOT1 sensitized the cancer cells to glucose deprivation, which was partially counteracted by metabolic intermediates downstream of GOT1 like OAA and phosphoenol pyruvate." (PMID 39777342, 2024).
cancer (continued). "Asp, a vital rate-limiting product of GOT1-catalyzed reversible reaction, is crucial for cancer cells due to its roles in nucleotide synthesis." (PMID 39777342, 2024). "This review summarizes emerging insights on the metabolic roles of GOT1 in cancer cells and emphasizes the response of cancer cells to altered metabolism when the expression of GOT1 is altered." (PMID 39777342, 2024). "This review will dissect GOT1-related metabolic mechanisms and the molecular pathways about how GOT1 influences cancer progression." (PMID 39777342, 2024). "GOT1/2, enzymes involved in glutamine metabolism, are both upregulated by K-Ras, known as an oncogene, in cancer cells." (PMID 37714917, 2023). "GOT1 is involved in coordinating the glycolytic and the oxidative phosphorylation pathways in KRAS-mutated cancer cells." (PMID 36139528, 2022). "GOT1 is overexpressed in many cancers; thus, it has been identified as a potential therapeutic target." (PMID 36387145, 2022). "Recently, the cytosolic isoform GOT1 has gained increasing attention for its role in promoting cancer cell proliferation by influencing cellular glutamate/glutamine metabolism." (PMID 33271457, 2021). "Functional validation in vitro provided mechanistic support for a pivotal role for GOT1-dependent glutamate metabolism in redox balance and cancer progression." (PMID 32111915, 2020). "Upregulation of glutamate oxaloacetate transaminase 1 (GOT1), an essential and ubiquitous enzyme in glutamine metabolism, is present in many types of human cancer and correlates with poor prognosis." (PMID 32266153, 2020). "Apart from conversion of glutamate to α-ketoglutarate using glutamate dehydrogenase 1 (GLUD1), cancer cells utilize glutamic-oxaloacetic transaminase 1 (GOT1) to generate oxaloacetate from glutamine-derived aspartate." (PMID 32370075, 2020). "Mechanically, AO suppressed GOT1 activity by competitive binding to the activation site thus inhibited Gln metabolism, resulting in apoptosis in cancer cells." (PMID 31470862, 2019). "Proteomic analysis of LO revealed enrichment of proteins involved in metabolic processes relevant to cancer, including the metabolic enzyme aspartate transaminase (GOT1)." (PMID 29760691, 2018). "The GEPIA web tool was used to examine the GOT1 gene expression in 33 types of tumors and it showed a diversity of expression of GOT1 in the different types of cancer." (PMID 29751795, 2018). "Our results show that GOT1 plays a key role to coordinate glucose consumption and glycolysis for cancer cells to survive the stress of low levels of nutrients." (PMID 29751795, 2018). "Consistent with the increased glucose dependency in the GOT1-null 143B cells, treatment of different cancer cell lines with metformin also increased glucose dependency similarly to GOT1-null 143B cells." (PMID 29751795, 2018). "More recently, CRISPR-based genetic screening approaches have identified glutamic-oxaloacetic transaminase 1 (GOT1) as an essential gene for cancer cell proliferation under limiting mitochondrial electron transport chain function." (PMID 30104199, 2018). "The diversity of GOT1 expression is probably a result of the pivotal role of GOT1 in cancer metabolic plasticity." (PMID 29751795, 2018). "LOs were able to transfer GOT1 and increase glutamate production in recipient cells, suggesting an effect of LOs on metabolic functions in cancer cells." (PMID 29760691, 2018). "Taken together, these data do not only show the importance of GOT1 in supporting cancer cell proliferation, but also imply a complexity of the GOT1 function in cancer cell metabolism." (PMID 29751795, 2018). "Our study suggests an important role of GOT1 to coordinate the glycolytic and the oxidative phosphorylation pathways in KRAS mutated cancer cells." (PMID 29751795, 2018). "The aim of the present study was to address the role of GOT1 in the metabolic adaption of cancer cells." (PMID 29751795, 2018).
cancer (continued). "Up- or down-regulation of GOT1 most likely depends on cancer type, growth properties and micro environment." (PMID 29751795, 2018). "Further experiments are needed to elucidate how GOT1 can be targeted in treatment of cancers expressing high levels of GOT1." (PMID 29751795, 2018). "Withdrawal of glucose led to rapid death of both GOT1-null 143B and GOT1 siRNA knockdown A549 cancer cells compared to their controls." (PMID 29751795, 2018). "Cancer cells are able to control the aerobic glycolysis rate via GOT1 and thereby regulate the NADH/NAD+ ratio." (PMID 29751795, 2018). "Inhibition of GOT1 sensitized the cancer cells to glucose deprivation, which was partially counteracted by oxaloacetate and phosphoenol pyruvate, metabolic intermediates downstream of GOT1." (PMID 29751795, 2018). "Our data suggest that GOT1 is the main source of OAA necessary for cancer cells to maintain cell viability upon nutrient scarcity." (PMID 29751795, 2018). "Our results also show that the GOT1 pathway is dispensable for cancer cells when nutrients are sufficient." (PMID 29751795, 2018). "We newly identified GOT1 as an enriched enzyme in LO and that LO can promote glutamine metabolism in recipient cancer cells by transferring the protein." (PMID 25857301, 2015). "The GOT1 interactome is enriched with the targets of cancer-associated miRNAs, specifically mir34a - a promising cancer therapeutic, while the GOT2 interactome is enriched with proteins that interact with cancer-associated transcription factors." (PMID 42245720, 2026). "Adding aspartate can rescue cancer cells with electron transport chain damage from the proliferation inhibition, whether GOT1 inhibition directly induces mitochondrial dysfunction remains unclear." (PMID 41327788, 2025). "Aspartate aminotransaminase (GOT1) plays an important role in cancer development but its role in HNSCC remains unknown." (PMID 41327788, 2025). "In addition, exosomes released from cancer cells can contain aspartate transaminase 1 (GOT1) and miR-217." (PMID 40328736, 2025). "Since GOT1 plays a key role in abnormal glutamine metabolism, it may be a potential anti-cancer target." (PMID 38495490, 2024). "Disruption of GOT1 significantly impacts Asp synthesis and consequently affects cancer cell growth." (PMID 39777342, 2024). "In various diseases, GOT1 inhibits cancer development by ferroptosis." (PMID 39605941, 2024). "The body of this work involving GOT1 highlights several key points in cancer metabolism." (PMID 39777342, 2024). "In addition, lncRNAs and circRNAs usually affect cancer cell proliferation via sponging miRNAs targeted GOT1 directly." (PMID 39777342, 2024). "This process links the expression of GOT1 closely to cancer progression." (PMID 39777342, 2024). "GOT1, an essential glutamine metabolism enzyme, is upregulated in many types of cancer." (PMID 36499136, 2022). "The effects of GOT1 on cancer cells have been fully demonstrated in PDAC." (PMID 35978348, 2022). "The GOT1 independence of CRC cell lines provide further support that a therapeutic window may exist for systemically targeting GOT1 in a subset of cancer types." (PMID 31908776, 2020). "In the current study, we set forth to determine whether the tissue of origin impacts GOT1 dependence to understand which cancers are most likely to benefit from this emerging therapeutic strategy." (PMID 31908776, 2020). "Glutamate oxaloacetate transaminase 1 (GOT1) is crucial for promoting cancer progression by regulating glutamate metabolism, and inhibition and silencing of GOT1 had been validated as an effective strategy to impair cancer growth." (PMID 33276753, 2020). "GOT1 as an essential in situ metabolic target of OAA had been demonstrate that selective inhibition of GOT1 with specific siRNA species decreases the proliferation of cancer cells." (PMID 31470862, 2019). "Our data suggest GOT1 as a possible target in cancer therapy." (PMID 29751795, 2018).